PCNA (proliferating cell nuclear antigen)
Diseases named in the same sentence as PCNA in open-access papers (continued):
Sharing a sentence is not in itself a finding about the gene and the disease.
glioma (continued). "All these results suggest that FKBP10 interacted with Hsp47, promoted the phosphorylation of AKT and CREB, upregulated the expression of PCNA mRNA and PCNA protein level, and thus enhanced the proliferation ability of glioma cells." (PMID 33557829, 2021). "The level of proliferating cell nuclear antigen (PCNA) expression in glioma was downregulated by Astragaloside IV, a major constituent of Astragalus membranaceus." (PMID 34031264, 2021). "PCNA protein levels were elevated while the ratio of cleaved-caspase 3/total-caspase 3 was elevated in glioma cells with circ_0082375 knockdown." (PMID 34868669, 2021). "Glioma cell proliferation indexes were assessed by stained for proliferating cell nuclear antigen (PCNA) and Ki-67, two indicators for cell proliferative ability, in xenograft tissues." (PMID 34696771, 2021). "Especially, we observed that FKBP10, via interacting with Hsp47, increased the phosphorylation level of AKT at Ser473 and CREB at Ser133, which promoted the transcription of PCNA and the proliferation of glioma cells." (PMID 33557829, 2021). "Meanwhile, the protein levels of Ki-67 and PCNA in tumor tissues derived from OR7E156P silenced glioma cells were significantly decreased compared to those in tumors derived from Lsh-NC-infected glioma cells." (PMID 34422645, 2021). "We found that whereas H3.3 mutant gliomas were highly proliferative as revealed by PCNA staining, they exhibited low 53BP1 NB counts in comparison to histone wild-type glioma biopsies." (PMID 34752469, 2021). "The anti-tumor activity of miR-149 in glioma cells was found to be correlated with low-expression of PCNA, p-AKT1, cyclin D1, and MMP-2." (PMID 31297133, 2019). "SMAD2+ glioma cells were highly enriched for the DNA polymerase factor, PCNA, consistent with the conclusion that this cell population housed the majority of dividing cells." (PMID 31602000, 2019). "Both T4 and T3 act as stimulators that induce proliferating cell nuclear antigen (PCNA) accumulation in glioma cells via activation of MAPK/ERK1/2." (PMID 31600974, 2019). "Expression of proliferation marker proteins, including cyclin D1 and proliferating cell nuclear antigen (PCNA), was significantly downregulated as well in circPRKCI-silenced A172 glioma cells." (PMID 31409777, 2019). "The stronger staining intensity and the increased number of hyperproliferative Ki-67 and PCNA positive tumour cells in TFP-treated nude mice suggested that TFP also promotes glioma cell growth in vivo." (PMID 29348654, 2018). "Our results showed that the ERK/p-ERK and PCNA protein expressions were increased in BzATP-treated glioma cell lines." (PMID 29546069, 2018). "SDC1 knockdown attenuated proliferation and invasion by glioma cells and markedly decreased PCNA and MMP-9 mRNA and protein expression." (PMID 28422726, 2017). "The results showed that NP-Pt treatment of U87 and U118 glioma cells decreased the level of DNA synthesis and the migration of cancer cells but also downregulated the level of PCNA protein expression in tumour tissue." (PMID 28562655, 2017). "Recent studies showed that the intratumoural injection of NP-Pt decreased PCNA protein expression in glioma tumours." (PMID 28562655, 2017). "On the other hand, GDNF up-regulates the expression of Ki67, PCNA and cyclins in the rat C6 glioma cell line." (PMID 28878618, 2017). "Immunohistochemical staining of PCNA and TUNEL assays demonstrated that high Cry2 expression in glioma tissues was associated with increased cell proliferation and decreased apoptosis." (PMID 29100427, 2017). "In glioma brain tissues, the proportion of proliferating cells (PCNA+ve) were 69.4% at ZT8 when cry2 expression was maximal compared to 34.7% at ZT4 when cry2 expression was lowest (p<0.01)." (PMID 29100427, 2017). "Cell morphology, the level of DNA synthesis, the migration of cells, protein expression levels of proliferating cell nuclear antigen (PCNA) and the level of DNA oxidation in glioma tumours were investigated." (PMID 28562655, 2017).
glioma (continued). "Sr-a1−/− glioma had a more robust proliferation index than Sr-a1+/+ glioma as evidenced by IHC staining of PCNA." (PMID 27367025, 2016). "The Pax3-induced high-grade gliomas harbored increased proliferation compared to the low-grade tumors induced by PDGF-B alone based on PCNA staining." (PMID 25330836, 2014). "The LIs of Ki-67 and PCNA were significantly lower in the normal brain tissues as compared to the gliomas." (PMID 24741354, 2014). "Here, we show that the disruption of Dnmt1/PCNA/UHRF1 interactions promotes a global DNA hypomethylation in human gliomas." (PMID 20613874, 2010). "Interestingly, studies have found that the upregulation of PCNA promotes the malignant proliferation of glioma cells." (PMID 39555702, 2024). "Similarly, it has been reported that PCNA is involved in the proliferation and metastasis of glioma cells." (PMID 39555702, 2024). "Finally, we conducted a study on the correlation of POLD4 expression with cell proliferation markers PCNA, tumor-associated macrophage markers (CD163, CD206), and the immune checkpoint PDL1 in glioma tissue." (PMID 37762224, 2023). "In addition, repressed PCNA mRNA and protein expression was observed after circ-SMAD7 was knocked down in the glioma cells, suggesting circ-SMAD7 promotes proliferation and metastasis of glioma via upregulating PCNA." (PMID 34858485, 2021). "A previous in vitro study showed that the PCNA-MGMT complex forms in glioma cells and could be inhibited by p21, a cell cycle inhibitor." (PMID 33585189, 2020). "In an animal experiment, the GDNF stimulation of rat glioma cells increased the expression of PCNA and Ki-67 and enhanced the proliferation of tumor cells, and in our research, the expression of both PCNA and Ki-67 were increased in patients with nonlocal recurrence." (PMID 33585189, 2020). "Our results are similar to previous results about the anticancer properties and antiproliferative properties of nanoplatinum, where NP-Pt of 5–8 nm in size mediated cell growth arrest, downregulated PCNA protein expression and activated apoptosis in U251 glioma cells." (PMID 28562655, 2017). "Meanwhile, positive correlations were found between DcR3 expression and Ki-67, PCNA Lis; that is, in the higher actively proliferated gliomas, the positive expression of DcR3 showed stronger expression, which indicates that DcR3 is closely related to the proliferation of glioma cells." (PMID 24741354, 2014). "We demonstrated that miR-195 promotes glioma cell proliferation by directly targeting the 3′-UTRs of cyclin D1 and cyclin E1, consequently reducing phosphorylation of pRb and downregulating the proliferative marker PCNA." (PMID 23383003, 2013). "Moreover, we demonstrated that upregulation of miR-195 in glioma cells led to the downregulation of phosphorylated pRb and proliferative marker PCNA through downregulation of cyclin D1 and cyclin E1 via directly targeting the 3′-UTR of cyclin D1 and cyclin E1." (PMID 23383003, 2013). "Conversely, inhibition of miR-195 promoted cell proliferation, increased the percentage of S phase cells, reduced the percentage of G1/G0 phase cells, enhanced anchorage-independent growth ability, upregulated the phosphorylation of pRb and PCNA in glioma cells." (PMID 23383003, 2013). "Furthermore, overexpression of miR-195 downregulated the levels of phosphorylated retinoblastoma (pRb) and proliferating cell nuclear antigen (PCNA) in glioma cells." (PMID 23383003, 2013). "Notably, proliferation of glioma cell lines is stimulated by THs, as demonstrated by accumulation in treated cells of the proliferating cell nuclear antigen (PCNA), and by an increase of radiolabeled thymidine incorporation into newly synthesized DNA in T4-treated cells in culture." (PMID 34070729, 2021).
glioma (continued). "PCNA, which is an antigen characteristic of proliferating cells that is expressed in cell nuclei during the S phase of the cell cycle, is a widely recognized cell proliferation marker that also serves as a prognostic indicator for a variety of tumors, including glioma." (PMID 33585189, 2020). "Furthermore, our study also showed that exosomes promoted proliferation, migration and invasion as well as inhibited apoptosis of glioma cells, enhanced the volume of tumor and Ki67 and PCNA expression as well as reduced the percentage of CD8+T cells in glioma mice." (PMID 32231463, 2020). "Moreover, the proliferation of glioma cells is correlated with a high degree of tumour malignancy, which can be evaluated by measuring the protein expression of proliferating cell nuclear antigen (PCNA)." (PMID 28562655, 2017). "In addition, PCNA was examined as a possible proliferation indicator in glioma cells." (PMID 29089868, 2017). "Western blotting analysis revealed that the phosphorylated pRb (p-pRb) and proliferative marker PCNA were also decreased in the miR-195-transfected cells and increased in the miR-195-inhibited cells, further demonstrating that miR-195 plays an important role in the proliferation of glioma cells." (PMID 23383003, 2013). "FOSL1 and JUN are the downstream factors in the PI3K/Akt pathway, and they can form a stable heterodimer known as AP-1, a transcriptional activator that can influence glioma behavior, reflected by elevated levels of phenotype markers BCL2 and PCNA." (PMID 39554845, 2024). "We collected tumor tissue samples from 20 glioma patients and performed immunohistochemical staining for POLD4, PCNA, CD163, CD206, and PDL1." (PMID 37762224, 2023). "We found that compared to the low POLD4 expression group, the high POLD4 expression group exhibited higher levels of PCNA, CD163, CD206, and PDL1 expression in glioma tissue." (PMID 37762224, 2023). "The results of immunochemistry in glioma tissues displayed that positive immunostaining of Hsp47, CREB (Ser133) and PCNA were abserved in glioma tissues." (PMID 33557829, 2021). "It has been reported that in glioma cells, CREB is constitutively activated, and PCNA is co-regulated by both CREB-dependent and -independent mechanisms." (PMID 33557829, 2021). "Analysis of TCGA datasets in glioma patients confirmed significant positive correlation of ITGA6 expression with CDK1, CDK4, PCNA, and FOXM1 transcript levels." (PMID 34205341, 2021). "In the present study, we observed that PCNA was highly expressed and positively related to the level of p-CREB in glioma tissues." (PMID 33557829, 2021). "Exosomes enhanced the volume of tumor, Ki67 and PCNA expression, reduced the percentage of CD8+T cells in glioma mice." (PMID 32231463, 2020). "Out of the 13 signature genes, ATP6V1E1, EIF3D, ERCC1, GPNMB, MTDH, PCNA and NEDD9 have been reported to play crucial roles in various pathways and mechanism of glioma." (PMID 31632497, 2019). "S127 and S143 phosphorylations mediated by PKC (protein kinase C) and AKT (also called PKB, protein kinase B) were observed in glioma and provoked the disruption of DNMT1/PCNA/UHRF1 complex and a consecutive global DNA hypomethylation." (PMID 29449903, 2018). "Next, we measured the effects of irradiation (15Gy) on cell proliferation in glioma and normal brain tissues when CRY2 levels were either high or low by PCNA immunohistochemical analysis." (PMID 29100427, 2017). "Mechanistically, overexpression of KIAA0247 is able to inhibit phosphorylation of AKT and Stat3 in glioma cells, resulting in inactivation of the AKT and Stat3 signaling pathways, this ultimately decreases the expression of PCNA, CyclinD1, Bcl2 and VEGF." (PMID 27893430, 2016). "Consistent with MRI results, PCNA, VEGF and CD31 immunohistochemical staining revealed that Sr-a1+/+ to Sr-a1−/− transplantation led to reduced proliferation and angiogenesis in gliomas." (PMID 27367025, 2016).
glioma (continued). "In the present study, we firstly reported that GCN5 was frequently overexpressed in human glioma tissues and GCN5 was positively correlated with proliferation of cell nuclear antigen PCNA and matrix metallopeptidase MMP9." (PMID 26378521, 2015). "PCNA staining of PTEN +/+ and PTEN −/− gliomas demonstrated a slight qualitative decrease in proliferation for perifosine treated animals with a more profound decrease seen in CCI-779 and in the combination treatment groups." (PMID 21267448, 2011). "We then demonstrate that the Dnmt1 phosphorylations by Akt and/or PKC abrogate the interactions of Dnmt1 with PCNA and UHRF1 in cellular and acelluar studies including mass spectrometric analyses and the use of primary cultured patient-derived glioma." (PMID 20613874, 2010). "In GSC xenograft models, both proliferating cell nuclear antigen (PCNA) and Nestin expression are positive, with Nestin levels showing a positive correlation with the degree of differentiation, malignancy, migration, and invasion of glioma cells." (PMID 41141394, 2026). "The increased expression of tumor-suppressors is common in many cancer types, including cyclin dependent kinase inhibitor p16Ink4a in glioma and HPV-induced cancers, CDK4/6 inhibitor p18Ink4c in cervical cancer and glioblastoma, and CDK2 and PCNA inhibitor p21 in many types of cancer." (PMID 40568073, 2025). "As expected, the high-POLD4 group showed significantly higher expression of PCNA, CD163, CD206, and PDL1 compared to the low-POLD4 group, further confirming the correlation between POLD4 and glioma cell proliferation and the immunosuppressive microenvironment." (PMID 37762224, 2023). "Additionally, our in vivo studies demonstrated that ar-turmerone suppressed glioma cell proliferation and reduced KI67 and PCNA expression in tumor tissues." (PMID 37768200, 2023). "CACNG3 could inhibit glioma growth, as CACNG3 overexpression decreased the proliferation markers of the tumor (Ki67 and PCNA)." (PMID 37697240, 2023). "Therefore, we analyzed the expression of PCNA in the low-POLD4 group and the high-POLD4 group to assess the impact of POLD4 on glioma proliferation." (PMID 37762224, 2023). "Interstingly, CACNG3 overexpression decreased the expression of Ki67 and PCNA, the proliferation markers of the tumor, which suggests CACNG3 could inhibit glioma growth." (PMID 37697240, 2023). "In addition, the overexpression of LACTB can inhibit the expression of PCNA, MMP2, MMP9 and VEGF, which are believed to play an important role in the proliferation, invasion and angiogenesis of glioma cells." (PMID 33507917, 2021). "PCNA was served as a DNA clamp for DNA polymerase to participating in DNA replication; cyclin D primarily controls the transition in mammalian cells from phase G1 to phase S, indicating that the knockdown of MICAL2 inhibited the proliferation of glioma cells." (PMID 34868922, 2021). "Additionally, gliomas with high FKBP10 expression tend to own high expression level of p-CREB (Ser133) and PCNA (P = 1.57E-9 and 0.0009, respectively)." (PMID 33557829, 2021). "Similarly, stable SHPRH, as an E3 ligase, ubiquitinated proliferating cell nuclear antigen (PCNA), thus inhibiting glioma cell proliferation and tumorigenicity." (PMID 34106407, 2021). "Then PCNA, MMP-2 and MMP-9 were costained in U251 and T98G cells with immunofluorescence staining assays, the result further showed that unigene56159 silencing suppressed the MMP-2 expression in glioma cells." (PMID 31789416, 2020). "Furthermore, immunochemistry staining for the proliferation marker, PCNA, indicated that suppression of SKA1 significantly inhibited glioma proliferation in vivo." (PMID 31827398, 2019). "In addition, the expression of ERK, p-ERK, and proliferating cell nuclear antigen (PCNA) protein was increased in BzATP-treated U87 and U251 glioma cells." (PMID 29546069, 2018).
glioma (continued). "In addition, AKT and STAT3 has been confirmed to be involved in the regulation of downstream factors including PCNA, Bcl2, CyclinD1 and VEGF, which are related to tumor proliferation, apoptosis and angiogenesis in glioma cells." (PMID 27893430, 2016). "We also examined PCNA and MMP9 expression in glioma tissues by using Western blot and RT-PCR." (PMID 26378521, 2015). "In addition, GCN5 knockdown reduced expression of p-STAT3, p-AKT, PCNA and MMP9 and increased the expression of p21 in glioma cells." (PMID 26378521, 2015). "We also reported that GCN5 expression was correlated with PCNA and MMP9 in glioma tissues." (PMID 26378521, 2015). "Our data indicated that the use of an unspecific DNMT inhibitor (5aza-2deoxycytidine), a DNMT1 inhibitor (procainamide) or peptides disrupting the DNMT1/PCNA, DNMT1/EZH2, DNMT1/HDAC1, DNMT1/DNMT3b and DNMT1/HP1 interactions promoted or enhanced in vivo tumorigenesis in a mouse glioma model." (PMID 23809695, 2013). "Yin and colleagues have explored hnRNPA2/B1-mediated mechanisms in promoting glioma growth and they have found that hnRNPA2/B1 activates the AKT-STAT3 signaling pathway to increase expressions of B-cell lymphoma-2 (BCL-2), CyclinD1 and proliferating cell nuclear antigen (PCNA)." (PMID 38072944, 2023). "In gliomas, a downregulation of LACTB leads to an increase in cancer cell proliferation and angiogenesis, corresponding to a poor prognosis in patients, while its overexpression does the opposite by inhibiting PCNA, MMP2, MMP9, and VEGF, which are key regulators in glioma cell proliferation." (PMID 34361072, 2021). "In addition, our findings demonstrated that FOXN3 over-expression triggered an obvious reduction in PCNA, CCND1, MMP9 and Vimentin expression levels in glioma cells, whereas FOXN3 ablation elicited a remarkable elevation in PCNA, CCND1, MMP9 and Vimentin expression levels." (PMID 34511432, 2021). "Moreover, downregulating SCD1 could decrease the expression of PCNA and MMP-9; thus, the proliferation and invasion of glioma cells were weakened." (PMID 33585189, 2020). "The disruption of the Dnmt1/PCNA interactions is also confirmed by the use of a proximity ligation in situ assay (P-LISA) and the significant reduction of the Dnmt1/PCNA interactions in U251 cells (a glioma cell line) compared with Astro#40 cells (a non-tumor glial cell lines) (p = 0.003)." (PMID 20613874, 2010). "However, despite its role as an oncogene, only recently it has been proposed in human glioma cells a mechanism for the regulation of CCNE1 activity that involves the miR-195 and leads to the reduction of pRb phosphorylation and to the downregulation of the proliferative marker PCNA." (PMID 26880947, 2016). "The result showed that PCNA and MMP9 were also upregulated in glioma tissues compared with non-tumor tissues both at mRNA and protein level." (PMID 26378521, 2015).